EGFR (epidermal growth factor receptor)
Diseases named in the same sentence as EGFR in open-access papers (continued):
Sharing a sentence is not in itself a finding about the gene and the disease.
tumor (continued). "First-line sensitivity to EGFR-TKIs in NSCLC has been associated with pre-existent AKT activation, and EGFR-TKIs fail to block AKT signaling in tumor cells that are intrinsically or extrinsically resistant to these drugs." (PMID 35931945, 2022). "Consistent with observations in Jurkat cells, hinge truncation progressively diminished the ability of EGFR-sdCAR-T cells to kill SKOV3 tumor cells and undergo CAR-T cell expansion." (PMID 35935988, 2022). "Compound 274 was found to be more effective in reducing the tumor size, and Western blot analysis revealed that it was selective in inhibiting EGFR phosphorylation." (PMID 35769445, 2022). "Histological analysis further revealed that the combined therapy reduced tumor proliferation and repair, and eradicated EGFR-expressing tumor cells." (PMID 36324626, 2022). "Tumour angiogenesis, resistance to apoptosis and overexpression of EGFR signalling pathways have been identified as factors contributing to tumour growth and metastasis." (PMID 35120511, 2022). "In yet another study EGFR was found to be expressed in 8 of 40 tumours and to correlate with mitotic activity." (PMID 35781872, 2022). "Previously, a proposed approach to the management of EGFR-mutant NSCLC progression on osimertinib was recommended: tumor biopsy of the progressive site should be accessed for evaluation of resistant mechanisms to indicate subsequent treatment." (PMID 35644609, 2022). "The univariate regression analysis showed that age, gender, tumor size, CEA, CYFRA21‐1, Ki‐67, tumor differentiation, and EGFR mutation were significantly associated with the solid components." (PMID 35289087, 2022). "The parental patients of PDX_489 and PDX_545 received anti-EGFR therapy, HNSCC_489 exhibited clinical benefit (−52.12%) and HNSCC_545 had a modest tumor response (−5.08%) and a brief progression-free survival (~1 month)." (PMID 35260570, 2022). "The GAS5 SNP rs145204276 Ins/Del + Del/Del illustrated a higher distribution with an advanced tumor stage (p = 0.030), larger tumor T status (p = 0.019), positive lymph node status (p = 0.014) and distal metastases (p = 0.011) in the EGFR wild type group." (PMID 36011604, 2022). "In 1993, a benzoporphyrin derivative (BPD) was conjugated to with a tumor-specific antibody against epidermal growth factor receptor (anti-EGFr), where binding through thiolmaleimide was used." (PMID 35200435, 2022). "The findings demonstrated similar results across all four groups, suggesting that either chemotherapy backbone in combination with either an anti-EGFR or anti-VEGF therapy is an acceptable therapy option in patients with RAS wt tumours." (PMID 36300092, 2022). "IRF9 and unphosphorylated STAT2 cooperate with NF-kB to induce IL-6 expression, a cytokine that promotes tumour growth of EGFR-driven GBM in an autocrine and paracrine manner." (PMID 36010867, 2022). "CCL21 has been previously shown to be downregulated in EGFR-driven tumours and contribute to an immunosuppressive TME, which can be confirmed by our data." (PMID 36010935, 2022). "The present study confirmed that TFAP2C knockdown enhanced the anti-tumor effects of cisplatin by decreasing cisplatin-induced activation levels of epidermal growth factor receptor (EGFR) and nuclear factor kappaB (NF-κB)." (PMID 36230734, 2022). "First, Liu and co-workers performed this method for ratiometric imaging of two biomarkers (EGFR, HER2) simultaneously in tumor xenografts with the help of three NP flavors - EGFR-NPs, HER2-NPs, and isotype-NPs." (PMID 35198078, 2022). "Previous studies have confirmed that circRNAs can affect the proliferation of tumor cells by regulating the expression of EGFR in lung cancer, colorectal cancer, glioblastoma, melanoma and other malignant tumors." (PMID 36483049, 2022). "Overall, 11 pretreatment factors, including PS, stage, EGFR mutation, morphology, TKI use, and tumor metastases were identified." (PMID 35205720, 2022).
tumor (continued). "PRODH has been involved in NSCLC metastasis as shown, both in vitro and in vivo, and ADORA1, which is highly expressed in EGFR-mutant NSCLC biopsies, has been associated involved in tumor-immune evasion in NSCLC xenograft models." (PMID 36551790, 2022). "Taking the EGFR expressed model as an example, the 3D tumor model showed a slightly higher sensitivity to the EGFR targeted drug of the gefitinib." (PMID 36313330, 2022). "In general, TCTP drives malignant phenotypes and the cross-resistance of tumor cells to chemo- and irradiation therapies by regulating oncogenic pathways such as the EGFR-AKT pathway." (PMID 35440620, 2022). "As the preceding results showed that LPCAT1-mediated gefitinib resistance of PC-9R cells is closely associated with the EGFR/PI3K/AKT pathway, we next verified this result by establishing a tumor-bearing mouse model." (PMID 35399731, 2022). "Concomitantly, m6A-seq unraveled that m6A-mediated modification of EGFR mRNA is induced by sublethal heat stress, which in turn promotes its binding with YTHDF1, leading to the upregulation of EGFR translation to promote tumor metastasis." (PMID 35884552, 2022). "Activating mutations in KRAS exon 2 can induce infinite proliferation of tumor cells, thereby freeing the pathway from the control of EGFR." (PMID 36465411, 2022). "In our study, the salivary EGFR levels in OSCC were high, attributed to high EGFR levels in actively dividing tumor cells." (PMID 36010285, 2022). "Our meta‐analysis aims to clarify the prognostic role of the EGFR‐plasma test in mutant tumor NSCLC treated with EGFR TKIs." (PMID 34427045, 2022). "After the CAR-T-cell invasion into the organoids, the EGFR-positive tumor cells were successfully killed, while the EGFR-negative tumor cells survived treatment." (PMID 36497454, 2022). "Patients who had at least KRAS, NRAS, BRAF, PIK3CA, or EGFR had a longer PFS (33.1 vs. 12.3 months) than patients with wild-type tumours treated with erlotinib." (PMID 36140214, 2022). "Some studies have shown that EGFR-TKIs can induce the immunogenic apoptosis of tumor cells, recruit T cells or upregulate the expression of PD1/PD-L1." (PMID 35935943, 2022). "These genes codify the multifunctional Ser/Thr kinase glycogen synthase kinase 3α and β isoforms, which are components of the EGFR/AKT pathway and are associated with tumor development, angiogenesis, metastasis, and drug resistance." (PMID 35681787, 2022). "EVs modified with GE11 peptide bind specifically to the epidermal growth factor receptor (EGFR), which is highly expressed on the surface of tumor cells and is a receptor target in the cancer drug delivery system." (PMID 36175866, 2022). "This system was found to exhibit an antagonistic effect on EGFR expression resulting in receptor expression internalization and downregulation and subsequent inhibition of the tumour cells proliferation." (PMID 36071488, 2022). "In NSCLC with EGFR mutation, activation of signal transducer and activator of transcription (STAT) and/or Akt is involved in tumor proliferation." (PMID 35399416, 2022). "In this study, we found that the upregulation of NK1R in NSCLC tumor tissues was positively related to the expression level of EGFR." (PMID 35013118, 2022). "Here we presented evidence for the novel role of NK1R in NSCLC tumor progression through its crosstalk with EGFR." (PMID 35013118, 2022). "EGFR regulates epithelial tissue development and homeostasis and drives tumorigenesis, and it has been recognized as a biomarker of tumor resistance." (PMID 36438905, 2022). "The median time from EGFR-TKI initiation to tumor resection was 5.9 [3.0–9.3] and 4.3 [3.5–7.4] months in patients receiving first-generation and second-generation EGFR-TKI, respectively." (PMID 36581631, 2022).
tumor (continued). "In mechanism, activation of EGFR signaling pathway in tumor would up-regulate VEGF expression, hence sensitize to anti-angiogenic therapies." (PMID 35296087, 2022). "In advanced tumor stages, IIIB–IV, we found EGFR mutations in 12.0% (78/650) of ACAs, in 1.1% of SCCs (1/87; p.Glu865Lys), and in 6.7% of ASCs (1/15; p.Ser768_Asp770dupSerValAsp)." (PMID 36293366, 2022). "In contrast to EGFR CAR T cells which are actively eradicating tumor cells, BDCA-2 CAR T cells are more potent in their GvHD response." (PMID 35836798, 2022). "A similar approach was employed to develop an IT of Her2/neu scFv-gelonin toxin and an EGFR-targeting ADC of RN765C to mitigate on-target/off-tumor toxicity by modulating the affinity of the cancer antigen targeting moiety." (PMID 36555466, 2022). "The plasma EGFR mutation assay can overcome the limitation of tumor tissue availability, shorten the TTI, and facilitate 1st line EGFR-TKI therapy for patients with treatment-naïve stage IV NSCLC, especially in the region of high-prevalence of EGFR mutation." (PMID 35207417, 2022). "The direct mechanism by which mAbs induce tumor cell death includes the blockade of growth factor receptor signaling, (anti-EGFR mAbs), or blocking ligand binding and receptor dimerization (anti-EGFR/HER2 heterodimerization and activation)." (PMID 35804808, 2022). "Tumor-specific targeted delivery of 5FU using EGFR aptamers as the carrier achieved high target specificity, overcame 5 FU resistance." (PMID 36339551, 2022). "Regarding IFNγ expression, we noticed similar trends of increasing levels in tumour tissue upon EGFR inhibition in the erlotinib-treated mice." (PMID 36010935, 2022). "In detail, CAR-Ts redirected using these targeting modules mediated effective target antigen-dependent tumor cell lysis both in vitro (against EGFR-expressing A431 and FaDu cell lines) and in vivo (in preclinical mouse models established using A431 cells)." (PMID 35468841, 2022). "In this study, enriched CAFs distribution was observed in EGFR TKIs resistant tumor tissues isolated from NSCLC patients." (PMID 35831824, 2022). "For the therapeutic group, the volume of tumor decreased sharply, resulting in a declined afterglow signal, thus indicating the decrease of EGFR-related signal pathway activity." (PMID 35105871, 2022). "Antibodies are now a mainstay cancer treatment, specifically targeting tumour (e.g. anti‐EGFR and HER2) or immune cells (e.g. anti‐CTLA4, PD‐1 and PD‐L1)." (PMID 35218154, 2022). "summarized that ROR1 was involved in inhibiting cell apoptosis, enhancing the EGFR signaling pathway, and inducing tumor epithelial-mesenchymal transformation (EMT)." (PMID 35935930, 2022). "There was a progressive increase in tumor growth in all mice with decreasing therapeutic activity with shorter hinge domain EGFR-sdCARs." (PMID 35935988, 2022). "Six main associations were described: radiogenomic prognosis, MGMT status, IDH, EGFR status, molecular subgroups, and tumor location." (PMID 35330402, 2022). "As a result, EGFR when measured by quantitative and semiquantitative immunohistochemistry (IHC), is generally known as an independent prognostic factor for tumor recurrence in OSCC patients." (PMID 35957892, 2022). "Preclinical studies have shown that EGFR activation can upregulate the expression of endogenous PD-L1 on tumor cells, thus inducing apoptosis of T cells and promoting immune evasion of EGFR-mutant NSCLC." (PMID 35935943, 2022). "Several studies have reported that SLCO4A1-AS1 promotes tumour growth and metastasis by potentially influencing the β-catenin/Wnt and EGFR/MAPK signal pathways." (PMID 35039060, 2022).
tumor (continued). "In a low EGFR expressing MDA-MB-453 tumor model, liver uptake showed about 2 %ID/g at 1 day and about 5 %ID/g at 7 days." (PMID 35890234, 2022). "For this purpose, we used a transgenic conditional mouse model to study the immunological profile in EGFR-driven NSCLC tumours." (PMID 36010935, 2022). "EGFR expression was heterogeneous, with greater fidelity for tumor presence in HNSCC and HGG than LAC (areas under the receiver-operating-characteristic curve, 0.96 and 0.94 vs. 0.82)." (PMID 35332092, 2022). "Inhibition of EGFR palmitoylation can enhance the efficacy of tumor therapy, showing a better clinical application value." (PMID 35637973, 2022). "EGFR (also known as HER-1), the expression product of proto-oncogene c-erbB-1, is closely related with tumor genesis and tumor development." (PMID 35252007, 2022). "EGFR is a glycoprotein with tyrosine kinase activity that is involved in tumour cell proliferation, angiogenesis, tumour invasion, metastasis, and apoptosis inhibition." (PMID 35702041, 2022). "c‐Jun N‐terminal kinase signalling executes either pro‐ or anti‐tumour function in different cellular contexts, depending on EGFR‐Ras signalling‐mediated switch of Yki activity." (PMID 35050535, 2022). "When healthy donor blood samples were spiked with variable amounts of different EpCAM+EGFR+ tumor cell lines, recovery yield was on average 75%." (PMID 36613466, 2022). "The two groups were similar in terms of age, sex, smoking history, ECOG PS, histologic subtype, EGFR and ALK tumor mutation status, PD-L1 TPS score and pretreatment NLR." (PMID 35627534, 2022). "Uncontrollable cell growth and malignant cell proliferation can occur upon the overexpression of EGFR-TK, and inhibiting the high expression of EGFR-TK has been proven to be an effective measure to reduce tumor growth and proliferation." (PMID 35517789, 2022). "Especially in tumor cells, radiosensitization upon β1 integrin and EGFR inhibition is gained by a reduced repair of radiation-induced DNA double strand breaks." (PMID 35194763, 2022). "EGFR overexpression not only leads to resistance to EGFR-targeted drugs but also leads to tumor resistance to multiple chemotherapy drugs." (PMID 35706930, 2022). "When tested in cellular cytotoxicity assays in vitro, the antibody induced EGFR-dependent cell death, and in tumor-bearing animals, recruited T cells to tumor xenografts." (PMID 36185288, 2022). "These EGFR-specificheterostructures sized 40 nm are effective both for cancer cell imaging viaCy5.5 labeling and for the hyperthermic effect on EGFR-overexpressingMDA-MB-468 tumor cells." (PMID 35441046, 2022). "In our study, we have demonstrated by both IHC and western blotting overexpression of EGFR in tumor tissue and its dose-related downregulation by PBPs." (PMID 36008552, 2022). "It has been demonstrated that the epidermal growth factor receptor (EGFR) pathway plays an important role in the growth, invasion and metastasis of tumor cells." (PMID 35898885, 2022). "Similar derivatives of the free primary amine, including isothiocyanates and maleimides (DFO-maleimide), have been reported for the 68Ga PET imaging of tumour-induced angiogenesis and 66Ga radiolabelling of EGFR, respectively." (PMID 36615397, 2022). "In these tumor entities, deregulation of the EGFR-NF-κB signaling pathway contributes to several important malignant properties of the tumor cells." (PMID 35203553, 2022).
tumor (continued). "Histologically, our model demonstrated a tumor with nests of pleomorphic cells, high levels of eosinophilic cytoplasm, and positive staining for both p40 (an established tumor marker) and EGFR." (PMID 35895055, 2022). "The predictive value of EGFR has been very well established using various methodologies such as immunohistochemical analysis of tumor samples, fluorescent in situ hybridization, tissue microarray, and gene sequencing." (PMID 35409179, 2022). "Meanwhile, EGFR has been reported as anti-tumor target due to its important role in cell proliferation and survival." (PMID 35873484, 2022). "Successfully inhibited tumor growth using EGFR-MET bispecific antibody in drug resistant PDX model supported our theory regarding the role of EGFR activation in the resistance to MET-targeted TKIs." (PMID 36338758, 2022). "Targets such as CEA, EGFR, EpCAM, MUC1, and VEGF were also highlighted as promising tumor-associated targets by the National Cancer Institute." (PMID 35053365, 2022). "Concerning patients who progressed on EGFR-TKIs, each line of treatment led to increased somatic genetic alterations in their ctDNA samples, reflecting the temporal tumor heterogeneity." (PMID 35884398, 2022). "Co-culture of tumor and effector cells at different E/T ratios for different times indicated that anti-EGFR CAR1-T, CAR2-T, and CAR4-T cells lysed ESCC cells in a dose- and time-dependent manner." (PMID 36551506, 2022). "Three different anti-EGFR mAbs (cetuximab, zalutumumab, and panitumumab) were equally efficient in the opsonization of tumor cell lines." (PMID 35035479, 2022). "Knockdown or blockade of EGFR remarkably reduced the size of tumor spheres and ability of clonal formation in both TNBC cell lines." (PMID 35725558, 2022). "Next, we employed haematoxylin and human EGFR antibody to detect tumour cells within tongue tissue and discovered that injected tumours had apparent EGFR membrane staining." (PMID 36448260, 2022). "Compared with cytotoxic chemotherapy, EGFR TKIs increase the tumor response rate to a greater degree, further prolong the PFS, cause fewer adverse effects, and improve the health-related quality of life." (PMID 36422186, 2022). "Here, the authors report that JHU083, an orally active glutamine antagonist prodrug designed to be preferentially activated in the tumor microenvironment, has potent anticancer effects on EGFR‐driven mouse lung tumorigenesis." (PMID 35861366, 2022). "The KEGG analysis showed that 57 genes were enriched in PI3K-Akt signaling pathway, PPAR signaling pathway, EGFR tyrosine kinase inhibitor resistance, and so on, suggesting that the 57 differentially expressed CCRGs play an important role in tumor progression." (PMID 36225197, 2022). "EGFR is associated with resistance to conventional cancer therapy; resistance to EGFR-targeted therapy can be attenuated via autophagy inhibition and thus represent a new mode of tumor treatment." (PMID 35645615, 2022). "In both cases, our predicted drug cocktails demonstrated high potency and achieved higher rates of tumor inhibition than anti-EGFR monotherapy." (PMID 35154483, 2022). "In three patients (patient 2, 3, and 5), anti-EGFR ILs-dox were administered 24 h before resection of tumor relapse, and in those cases doxorubicin levels were assessed in tumor tissue, in addition to plasma and CSF samples." (PMID 34998092, 2022). "Our results showed that DCZ0415 reduced the expression of p-EGFR and p-AKT, suggesting that the anti-tumor effect of DCZ0415 was involved in the EGFR/AKT signaling pathway." (PMID 35075117, 2022). "Through enhancing EGFR expression, we proved that EGFR mediated ACEA-caused changes in tumor growth and macrophage differentiation." (PMID 35641479, 2022).